IL10 (interleukin 10)
Diseases named in the same sentence as IL10 in open-access papers (continued):
Sharing a sentence is not in itself a finding about the gene and the disease.
infection (continued). "Within the CNS, IL-10 is produced by resident microglia and astrocytes as well as infiltrating leukocytes during neuroinflammatory diseases and IL-10 production is elicited in response to TLR2 signaling during S. aureus craniotomy infection." (PMID 37179295, 2023). "Conversely, the control groups failed to effectively control the infection and exhibited the elevated production of Th2-characteristic cytokines such as IL-10." (PMID 37569710, 2023). "Although some inflammatory mediators were altered in CX3CR1CreIL-10 fl/fl animals, this did not translate into less infectious burden, suggesting a minor role for microglial/monocyte-derived IL-10 in dictating infection chronicity." (PMID 37179295, 2023). "AAV2/1 infection of hippocampal neurons resulted in sustained expression of IL-10 without its leakage into the blood, reduced astro/microgliosis, enhanced plasma Aβ peptide levels, and enhanced neurogenesis." (PMID 36936500, 2023). "Similarly, on day 7 after infection, the levels of TNF-α, IL-6, and IL-10 were higher in ΔPbMAP1-infected mice." (PMID 37563696, 2023). "Infection with all three strains (HN878, rpoB-S450L, and rpoB-H445Y) resulted in increased production of other cytokines that were measured, such as the pro-inflammatory IL-6 and the anti-inflammatory IL-10." (PMID 37682004, 2023). "Infection of neutrophils and HL-60 cells produce striking quantities of chemokines, including IL-8, RANTES, MIP1α, MIP1β, and MCP1, but not other cytokines observed with in vivo infection, including IFNγ, IL-10, TNFα, IL1β, or IL4." (PMID 37228668, 2023). "Moreover, the expression of immune-related genes (SAA, iNOS, IL-1 β, IL-6, IL-10, TNF α, C3, MHC I, MHC II, CD4, CD8, TCR α, IgM, IgD and IgZ) increased in all groups post infection, which was more significant in the vaccinated groups." (PMID 36969197, 2023). "We have previously reported that a lack of MALAT1 results in lower levels of MAF and IL10 in mice and as a consequence, greater host resistance to infection or increased immunopathology." (PMID 36869729, 2023). "During an infection caused by Gram-negative bacteria, the synthesis of proinflammatory cytokines such as TNF-α and IL-1, IL-6, IL-8, and IL-10 is also more frequent." (PMID 37762882, 2023). "Our findings suggest that the levels of IL‐10 and IFN‐γ release may be promising biomarkers to predict subsequent infection in AH patients." (PMID 37125245, 2023). "The shift from M1 to M2 during the infection course was correlated with the secretion of Th1 cytokines (IFN-γ and TNF-α), changing to Th2 cytokines (IL-10 and IL-13), further indicating that M1 is related to the pro-inflammatory response and M2 to the Th2/regulatory response." (PMID 36668953, 2023). "The basic pathologic feature of postinfectious LA is the development of an excessive, dysregulated proinflammatory immune response during the infection characterized by high IFN-γ levels and inadequate levels of the antiinflammatory cytokine IL-10, which persists in the postinfectious period." (PMID 37471146, 2023). "However, BA.5 and its parental strain, B.1.1.529, infection leads to the similar frequency of IFN-γ, IL-17A, IL-10-producing CD4+ T cells as well as IFN-γ, IL-10-producing CD8+ T cells in BALF." (PMID 37704701, 2023). "In mice, R7 more effectively protected mice from infection with MDR E. coli or LPS and alleviated inflammation than its parental peptides by inhibiting the production of proinflammatory cytokines (TNF-α, IL-6, and IL-1β) and promoting IAP and IL-10." (PMID 37973936, 2023). "We report that during infection of macrophages and dendritic cells with various intracellular bacteria, XIAP restricts cell death and secretion of IL-1β but promotes increased activation of NFκB and JNK which results in elevated secretion of IL-6 and IL-10." (PMID 37347786, 2023).
infection (continued). "In addition to the stimulation of golden pompano by Streptococcus agalactiae and infection of spleen and kidney necrosis virus (ISKNV) in mandarin fish (Siniperca chuatsi), IL-10 expression was significantly upregulated in the spleen after stimulation." (PMID 37513733, 2023). "This response was markedly subdued after antibiotic treatment and characterized by an increase of Th2 and Th IL-10+ cells, irrespective of infection status." (PMID 37898618, 2023). "In this study, the expression of carp IL-10 with or without infection of SVCV in epithelioma papulosum cyprinid (EPC) cells, carp head kidney (cHK) primary cells and common carp tissues were analyzed using RT-PCR and ELISA." (PMID 38004823, 2023). "However, infection by any of these SARS-CoV-2 strains resulted in a mild upregulation of the inflammatory markers including IL-1β, TNF-α, and IL-10 at 3 dpi." (PMID 38257760, 2023). "The results showed that the protein concentration of inflammatory cytokines in both types of mice was significantly increased after BMA8 strain infection, and the expression of cytokines was higher in BALB/c mice, including IL-2, IL-4, IL-6, IL-10, IL-12p70, KC/GRO, IFN-γ and TNF-α." (PMID 37081549, 2023). "Lastly, examination of cytokine production at later times after infection indicated that CD4+ T cells did not maintain their ability to produce IL-10 at a higher rate in the absence of Bhlhe40." (PMID 37843306, 2023). "In line with the higher bacterial load at peak infection, on day 3 Calhm6−/− mice showed a higher inflammatory response in serum, with increased levels of pro‐inflammatory cytokines IFN‐γ and IL‐6, and lower levels of anti‐inflammatory IL‐10." (PMID 36861806, 2023). "However, CLEC2.Fc efficiently inhibited the expression of proinflammatory cytokines (IL‐6, TNF‐α, IFN‐γ, and IL‐10) and chemokines (CXCL1, CXCL2, CXCL5, CCL2, IP‐10) at day 3 and day 5 post‐infection (blue columns)." (PMID 37211986, 2023). "Improved control of inflammation during 8067 and T15 infection compared to S10 infection is also evident in the significant increase in anti-inflammatory IL10 expression already at 4 hpi; this is not achieved until 24 hpi during S10 infection." (PMID 38276150, 2023). "The observation that Bhlhe40−/− CD4+ T cells exhibit a significant increase in IL-10 RNA and protein production suggests that Bhlhe40 acts during the early stages of a P. yoelii infection, to suppress IL-10 expression in CD4+ T cells, as it does in response to other Th1-centric infections." (PMID 37843306, 2023). "Additionally, at 12 days post-infection, the spleen of CKO mice showed a decrease in the number of CD4+ T cells producing IL-10 compared to WT mice." (PMID 37908369, 2023). "It is notable that in this report, IL-10 was among the genes that failed to increase during infection in the spleen of IL-27Rα-/- pups." (PMID 36891292, 2023). "RT-qPCR did not reveal significant differences in the amount of TMEV RNA as well as Ifnb1, Isg15, Eif2ak1 (PKR), Tnfa, Il1a, Il1b, Il6, Il10, Il12 (p40) and Ifng transcript numbers in the brain of Asc−/− and Casp1−/− mice and their respective wild type littermates at 4 days after TMEV infection." (PMID 37414913, 2023). "However, another study found that 18 days after infection, there is a significant increase in TNF-α and IL-10 levels in infected dogs, but this difference disappears after 30 days." (PMID 37627021, 2023). "Furthermore, IL-10 expression was upregulated during Mpgm-ATCC and Mpgm-R infection, and the same result was obtained via RT–PCR." (PMID 38133329, 2023). "In addition, although the transcription of various cytokines, such as IL-1β, IL-2, IL-4, IL-8, and IL-10, was shown to be highly upregulated to defend the organism against DHAV-(1/3) infection, the variation of duck IL-22 after DHAV infection is still unclear." (PMID 37391858, 2023).
infection (continued). "The resulting inhibition of LPS-induced pro-inflammatory (TNF-α, IL-1β, IL-6, IL-12) cytokine expression, and induction of regulatory cytokines (IL-10, TGF-β) indicates a role during infections in the modulation of macrophage responses towards phenotypes conducive to worm survival and host health." (PMID 35335634, 2022). "Our results showed that the concentrations of IL-4 and IL-10 in Co-PRRSV-PCV2 and PRRSV-PCV2 groups were significantly higher than the other groups, suggesting that adaptive immune responses were robust in these infection groups." (PMID 35215787, 2022). "In our study, we observed non-significant increases in IL-10 due to infection in non-senescent macrophage co-cultures, and a non-significant decrease in senescent macrophage co-cultures, which is again consistent with the collagen data that we observed." (PMID 36534613, 2022). "Several studies have shown that steE can promote IL-10 production via the activation of STAT3 signaling and metabolic and physiological environment reprogramming for Salmonella in B cells, changing it from an anti-inflammatory to an infection state." (PMID 35909683, 2022). "In SIV-infected macaques, levels of IL-10 in plasma and lymph nodes (LNs) were induced by infection and not normalized with antiretroviral therapy (ART)." (PMID 35230978, 2022). "Increases the production of IL-10 and reduces the expression of pro-inflammatory IL-12 and TNF-α; stimulates the migration of leukocytes; increases the expression of GM-CSF, IFN-γ, and MCP-1 in the early infection phase." (PMID 36009931, 2022). "Overexpression of TIGIT by lentivector infection of human CD4+T cells, the cell proliferation, cytokines secretion (IL-12, IFN-γ, and TNF-α), and T-bet expression were significantly hindered whereas IL-10 production was enhanced." (PMID 35720417, 2022). "The infection with Pa increased NAG and MPO activities (indicative for macrophages and neutrophils, respectively) and the concentrations of CXCL-1, IL-1β, IFN-γ, and IL-10 compared to the NI group." (PMID 35548467, 2022). "It is also probable that the low levels of CD8+ cells are the consequence of previous activation that occurred early during infection and that negative feedback signals (IL-10, TGF-β) downregulated the activity of T cells and reduced their numbers." (PMID 35372587, 2022). "At day 5 to 6 post infection, we observed an upregulation of IL-4, but not of IL-5, IL-10 or IL-13 mRNA." (PMID 35894051, 2022). "Although CD11c depletion at this stage of infection resulted in impaired liver cell potential to produce IL-4 and IL-10, it did not significantly impact Ag-specific cytokine responses." (PMID 35958580, 2022). "Accordingly, during infections a balanced equilibrium between MIF (pathogen control) and IL-10 (pathology control) may confer tolerance towards an infectious disease." (PMID 35464430, 2022). "Neither the frequency of Tregs nor their IL-10 expression was significantly affected by infection in either the SILP or MLN at this early timepoint, although IL-10 was again more strongly expressed in the SILP than the MLN." (PMID 35428872, 2022). "However, K1544Δcps-infected eyes had significantly increased quantities of IL9, IL10, IL12-p70, MIG, and MIP-1-gamma compared to K1544-infected and scratch control eyes 24 h after infection (p = 0.037, 0.007, 0.029, 0.037, and 0.036, respectively)." (PMID 35456761, 2022). "IL-10 plays a critical role in the ability of MAP to survive within host cells by shifting the nature of the host immune response to Th2, resulting in attenuated pro-inflammatory responses that are critical for the control of infection." (PMID 35211544, 2022). "The results from the current study showed a rapid expansion of B220+CD5+CD1d+ IL-10 producing regulatory B cells during infection with both lethal strain P. yoelii 17XL and non-lethal P. yoelii 17XNL at an early stage of infection." (PMID 35625397, 2022).
infection (continued). "For example, our pilot study showed a significant difference in the time course of IL-10 between patients with and without an infection at an earlier time point than 24 h." (PMID 36430226, 2022). "Overexpression of TIGIT by lentivector infection could hinder the function of CD4+ T cells, such as diminished IFN-γ and IL-17 production, and increased IL-10 expression." (PMID 35720417, 2022). "In addition, cytokines, including IL-6/IL-10/TNF-α/IFN-γ can be used for rapid and timely diagnosis of infection in children with hematological malignancy." (PMID 35463642, 2022). "On this regard, similar levels of IL-10 were detected in the animals infected with WT and A12-LH138L viruses consistent with equivalent levels of detectable neutralizing antibodies by 21 days post infection." (PMID 36387381, 2022). "Il5 and Il13 expression remained elevated in whole duodenal tissue at day 21 of infection, but this increase above naïve control was not statistically significant when IL-10 signalling was disrupted." (PMID 35428872, 2022). "In CLN, there were also elevated numbers and percentages of IL-17A-producing ILC3 cells in IL10-/- mice on day three but not day five after infection." (PMID 36016413, 2022). "On the other hand, anti-inflammatory cytokines interleukin-13 (IL-13), interleukin-4 (IL-4), interleukin-10 (IL-10) and transforming growth factor-β (TGF-β) appear on the fourth day after infection and ameliorate the exacerbation of inflammation and participate in the healing of lesions." (PMID 35053737, 2022). "In contrast, vaccination but not previous infection resulted in significantly lower levels of IL-10 in the lungs and spleen following challenge." (PMID 36032120, 2022). "During the assessment of the patients on the first day, vital signs (heart rate, blood pressure), infection indicators (WBC, PCT), inflammatory indicators (TNF-α, IL-10, IL-6), CVP, Norepinephrine (NE), oxygenation index (OI), CTNI, and NT-pro BNP were collected." (PMID 35729330, 2022). "Importantly, B7-H4−/− infection further regulated the expression of molecules (CD80, CD86, and MHC-II or HLA-DR), enzyme IDO, and cytokines (IL-10 and IL-12) in dDCs." (PMID 35505420, 2022). "Similar to H37Ra infection, we found that AM failed to produce cytokines, including IL-12p40, IL-6 and IL-10, but not TNFα, in response to H37Rv infection." (PMID 36776396, 2022). "The LCMV clone 13 strain establishes a persistent infection where long-lasting expression of IFN-β and IFN-α in cDCs leads to exhaustion of the protective Th1 cell response by a mechanism involving up-regulation of PD-L1 and IL-10 expression by the cDCs." (PMID 35911733, 2022). "In particular, macrophages produce IL-10 in a negative feedback loop to reduce uncontrolled inflammatory cytokine production during, for example, infection." (PMID 36362746, 2022). "TGFb1-positive ILCs were detected 3 days after infection and were more abundant in the absence of IL-10." (PMID 36016413, 2022). "However, after infection, the frequency of NK cells expressing IL-10 increased about 6-fold, and the frequency of NKT cells expressing IL-10 and TGF-β1 increased 13-fold and 8-fold, respectively." (PMID 35720410, 2022). "The difference was that IL‐10 was significantly higher than the control group at 30 days after infection, but IL‐4 was not." (PMID 36169259, 2022). "In addition, no significant alteration in the levels of IFNγ, IL-1β, IL-4, IL-6, IL-8, IL-10, CXCL10, and TNFα was observed in peripheral blood after Vir-S74-T3Bo infection by comparing Att-S74-T3Bo-inoculated and naïve control animals." (PMID 36466866, 2022). "In this study, compared with the overexpression of IL-10 in the Model group and the underexpression in the LEV group, QGYD-LEV treatment significantly increased the release of IL-10 in the early stage of infection to control the proinflammatory response at a moderate level." (PMID 35071595, 2022).
infection (continued). "In this regard, data from T. cruzi infection differs from those observed during infection with other intracellular parasites such as T. gondii and certain L. major strains, in which high frequencies of CD4+ T cells producing both IL-10 and IFN-γ were described." (PMID 35670567, 2022). "However, infection with LdCen-/- limits the expression of CD200 in CD11c+ dendritic cells, resulting in the reduction in IL-10 and the increase in IFN-γ and TNF-α production by CD4+ T cells." (PMID 35456106, 2022). "In this case, the frequency of cells producing TNF-α slightly increased, and IL-10 or TGF-β1 were not the prevalent cytokines produced after infection." (PMID 35720410, 2022). "CLA also increased the expression of interleukin-10, transforming growth factor (TGF)-β, and inducible nitric oxide synthase (iNOS) (P<0.05), while infection elevated the expression of Foxp3, with a peak at 40 days post-infection (P<0.05)." (PMID 36544518, 2022). "Lacking IL-10, the Th1 response modulator will aggravate the infection status and lead to greater immunopathology." (PMID 36560492, 2022). "Infection with Sj induced TGF-β- and IL-10-producing B cells while decreasing CR5+ B1a cells." (PMID 35461268, 2022). "Here, we observed that the production of inflammatory TNF-α and IL-1β and anti-inflammatory IL-10 was not changed following infection with Δnmo2 and Δnmo5 in contrast to infection with the wild-type strain." (PMID 35887491, 2022). "Furthermore, the release of IL-10 in the QGYD group and QGYD-LEV group decreased rapidly in the later stage of infection." (PMID 35071595, 2022). "It has been described that during symptomatic infection by Leishmania, IgDhi B cells produce IL-10 and suppress IFN-γ production in T cells through the PD-L1/PD-1 and IL-10 pathways, leading to the suppression of the T-cell response and cellular exhaustion in these dogs." (PMID 35746555, 2022). "Among the significantly enriched IPA canonical pathways, TREM1 and IL-10 signaling were enriched in both L. interrogans- and L. biflexa-infected BMDMs, regardless of the infection period." (PMID 35638785, 2022). "It is, therefore, likely that the other parapoxvirus IL-10s play a similar role during infection and reinfection, but deletion of the BPSV, PCPV, RDPV, and GSPV IL-10 genes in their respective viruses would be necessary to confirm their role in host pathogenesis." (PMID 35631028, 2022). "We tested the serum samples for classical inflammatory and anti-inflammatory cytokines as systemic markers for a prolonged immune response, and observed a trend for slightly elevated cytokine levels for IL8, TNFα, IL6, IL12p70, IL10, IL5 and IL4 in the first four months after the infection." (PMID 36293090, 2022). "Although the pathogenesis of VU is likely multi-factorial, our results indicate that the increase of specific inflammatory mediators, such as IL-6, IL-10, IL17A, and TNF-α in wound fluids can be found in the presence of an infection particularly when sustained by biofilm-producing bacteria." (PMID 36140047, 2022). "One study utilizing Plasmodium chabaudi chabaudi demonstrated that engraftment of wildtype but not IL-10-deficient CD4+ T cells protected Rag-/- mice from serious weight loss, hypothermia, and mortality following infection." (PMID 36389662, 2022). "At 14 d post-infection, ZIL-treated mice displayed reduced serum level of IL-12 and IL-10." (PMID 36039381, 2022). "Moreover, the experimental infection resulted in increased LZM, as well as enhanced levels of inflammatory factors, including IL-1β, IL-6, TNF-α and IL-10 in serum, indicating activation of inflammatory response following E. coli inoculation." (PMID 36198724, 2022). "Importantly, beyond AIT, the contemporary synthesis of IL-10 and IFN-γ from the same T cell has been reported in pathological conditions including several infections, autoimmune disorders, and cancer, in which a chronic antigen stimulation occurs." (PMID 36359345, 2022).